LSM2 (LSM2 homolog, U6 small nuclear RNA and mRNA degradation associated)
Description:
Plays a role in pre-mRNA splicing as component of the U4/U6-U5 tri-snRNP complex that is involved in spliceosome assembly, and as component of the precatalytic spliceosome (spliceosome B complex). The heptameric LSM2-8 complex binds specifically to the 3'-terminal U-tract of U6 snRNA.
Synonyms: C6orf28; G7B; YBL026W; snRNP
Tractability: Small molecule: a structure with a bound ligand is known. PROTAC: ubiquitination databases record sites on it; its protein half-life has been measured.
Gene: Protein-coding gene on chromosome 6 (31,797,392 to 31,806,987, reverse strand). Ensembl gene ENSG00000204392.
Subcellular location: Nucleus
Subcellular location (Human Protein Atlas): Nucleoplasm
Pathways (Reactome):
Metabolism of RNA: mRNA Splicing - Major Pathway; mRNA decay by 5' to 3' exoribonuclease
Gene Ontology:
Molecular function: protein binding; RNA binding; small GTPase binding; U6 snRNA binding
Biological process: mRNA catabolic process; mRNA splicing, via spliceosome; spliceosomal tri-snRNP complex assembly; deadenylation-dependent decapping of nuclear-transcribed mRNA; spliceosomal snRNP assembly; mRNA processing
Cellular component: catalytic step 2 spliceosome; cytoplasm; Lsm2-8 complex; nucleoplasm; nucleus; precatalytic spliceosome; spliceosomal complex; U2-type precatalytic spliceosome; U4/U6 x U5 tri-snRNP complex; cytosol; Lsm1-7-Pat1 complex; P-body; U4/U6 snRNP; U4atac/U6atac snRNP; U4atac/U6atac x U5 tri-snRNP complex; U6 snRNP; U6atac snRNP
Genetic constraint (gnomAD): Loss-of-function variants: 12 observed, 17.2 expected, observed/expected ratio (o/e) 0.7, 90% interval 0.45 to 1.13. The upper end of that interval is the gene's LOEUF score, 1.13, which puts it in group 4 of 6, group 1 being the genes least tolerant of losing a copy. Missense variants: 62 observed, 116.18 expected, observed/expected ratio (o/e) 0.53, 90% interval 0.43 to 0.66. Synonymous variants: 42 observed, 46.62 expected, observed/expected ratio (o/e) 0.9, 90% interval 0.7 to 1.16.
Homologues: Orthologues: chimpanzee LSM2 (100% identical), dog LSM2 (100% identical), guinea pig LSM2 (100% identical), macaque LSM2 (100% identical), pig LSM2 (100% identical), mouse Lsm2 (99% identical), rat Lsm2 (99% identical), zebrafish LSM2 (99% identical), zebrafish smx5 (99% identical), Drosophila melanogaster CG10418 (92% identical), Caenorhabditis elegans gut-2 (83% identical).
Diseases named in the same sentence as LSM2 in open-access papers:
LSM2 is named in the same sentence as 81 diseases in open-access papers, as found by Europe PMC text mining. Sharing a sentence is not in itself a finding about the gene and the disease. The quoted sentences say what the papers report.
breast carcinoma (7 papers, 2018 to 2025). "This is consistent with previous studies linking elevated expression of LSM2 to malignancy in other cancers, such as breast cancer and hepatocellular carcinoma." (PMID 40365337, 2025). "Markedly upregulated LSM2 mRNA expression was also found in breast cancer (BRCA), pancreatic ductal adenocarcinoma (PDAC), and hepatocellular carcinoma (HCC)." (PMID 37312186, 2023). "Furthermore, when extracting the co-expression gene list from TCGA and METABRIC datasets, we observed that LSM2 was closely co-expressed with various breast cancer biomarkers such as PDCD5 and NUDT5." (PMID 34638387, 2021). "Consistently, other studies revealed LSM1, LSM2, LSM3, LSM12 as oncogenes which could play a crucial role in growth and progress of breast cancer, basal-like primary tumors, cervical carcinoma or colorectal cancer." (PMID 37007092, 2023).
lung carcinoma (6 papers, 2017 to 2024). "Germline variants and somatic mutations of LSM2, which belong to mRNA splicing-related genes, have been confirmed to be high-risk factors for lung cancer." (PMID 37312186, 2023). "Genetic variants of LSM2, an mRNA splicing protein, were confirmed to be associated with lung cancer." (PMID 37312186, 2023). "Similarly, genetic variants of LSM2 are associated with lung cancer risk." (PMID 36371223, 2022). "SNPs in DHX16 (rs115420460) and LSM2 (rs114312980, rs115489726, rs115801685, rs114637560, rs115834633) were excluded from further analysis due to their locations within the previously identified lung cancer susceptible region Chr6p21.33 and in high LD with previously reported lung cancer GWAS SNPs." (PMID 28304396, 2017). "Previous studies have shown that LSM2 plays a role in the disease progression of lung cancer." (PMID 36389112, 2022).
ovarian carcinoma (5 papers, 2022 to 2024). A malignant neoplasm originating from the surface ovarian epithelium. "Previous studies also revealed LSM2 as an independent predictor of poor prognosis in ovarian cancer." (PMID 37007092, 2023). "In ovarian cancer, the decrease in the degree of LSM2 methylation may lead to an increase in its expression, which results in a disorder in the processing and circulation of most RNA, affecting the expression of various proteins and accelerating tumor development." (PMID 36371223, 2022).
cutaneous melanoma (4 papers, 2022 to 2025). A primary melanoma arising from atypical melanocytes in the skin. "For example, LSM2 is upregulated in the tumor tissues of patients with cutaneous skin melanoma, and knockdown of LSM2 reduces the cell proliferation and migration of cutaneous skin melanoma cells." (PMID 40425760, 2025). "The expression profile of LSM2 in melanoma cell lines and normal skin was explored using the BioGPS database, and LSM2 was found to be expressed at elevated levels in cutaneous melanoma cell lines (p < 0.001)." (PMID 37312186, 2023). "The expression of LSM2 was assessed in the normal skin cell line (HEMa-LP) and cutaneous melanoma cell lines (A2058, A375, MeWo, SKMEL-2, and SKMEL-28) using RT-PCR." (PMID 37312186, 2023). "Not directly associated with skin pigmentation, LSM2, an mRNA splicing-related gene, is a risk factor proportionally regulated with cutaneous melanoma prognosis, regulating cell proliferation and apoptosis." (PMID 39063015, 2024). "In addition, in the BioGPS database, LSM2 was found to be highly expressed in cutaneous melanoma cells compared to normal skin cells." (PMID 37312186, 2023). "The protein expression of LSM2, LSM4, and LSM12 was upregulated in cutaneous melanoma." (PMID 36371223, 2022). "In this study, using knockout or knockdown techniques, most LSM2 dependency scores of the SKCM cell lines were < -0.5, indicating that knocking out or knocking down LSM2 mRNA could significantly affect the growth of cutaneous melanoma cell lines in the DepMap database." (PMID 37312186, 2023).
glioma (4 papers, 2014 to 2025). A benign or malignant brain and spinal cord tumor that arises from glial cells (astrocytes, oligodendrocytes, ependymal cells). "Our research leverages multi-omics approaches, including transcriptomic analysis and RNA sequencing, to systematically examine the expression of LSM2 in gliomas and its association with clinical outcomes." (PMID 40365337, 2025). "Analysis of TCGA data via cBioPortal revealed a low mutation frequency of LSM2 in gliomas (0% in LGG, 5% in GBM, predominantly amplifications/deletions)." (PMID 40365337, 2025). "LSM2, an RNA-binding protein, has been implicated in tumour progression, yet its role in glioma remains underexplored." (PMID 40365337, 2025). "In this study, we observed that LSM2 expression is closely associated with immune cell infiltration levels in gliomas." (PMID 40365337, 2025). "This is further supported by our survival analysis, where high LSM2 expression was associated with shorter overall survival in glioma patients." (PMID 40365337, 2025). "Liquid biopsy techniques, such as circulating tumour DNA (ctDNA) analysis, could be explored to monitor LSM2 expression and its molecular network, further enhancing diagnostic capabilities for glioma." (PMID 40365337, 2025). "Moreover, the identification of key genes regulated by LSM2 provides potential biomarkers for glioma prognosis, which could help in developing diagnostic and therapeutic strategies." (PMID 40365337, 2025). "Immunohistochemical analysis of both high-grade and low-grade glioma tissues revealed strong nuclear localisation of LSM2, with moderate staining intensity." (PMID 40365337, 2025). "Our findings demonstrate that LSM2 plays a crucial role in glioma progression through its influence on various cellular pathways, such as the cell cycle, DNA repair, RNA splicing, and cell adhesion." (PMID 40365337, 2025). "This investigation employed an integrated multidimensional approach, incorporating bioinformatics prediction, gene knockout models and functional enrichment analysis, to systematically elucidate LSM2’s central regulatory role in glioma progression." (PMID 40365337, 2025). "This study establishes LSM2 as a central player in glioma progression, affecting multiple cellular processes such as RNA splicing, cell adhesion, and immune modulation." (PMID 40365337, 2025). "Our findings demonstrate that LSM2 plays a critical role in glioma progression through the regulation of RNA splicing dynamics." (PMID 40365337, 2025). "Elevated LSM2 expression serves as a prognostic biomarker and offers promising potential as a therapeutic target in glioma." (PMID 40365337, 2025). "This study aims to investigate the expression, prognostic significance, and molecular mechanisms of LSM2 in glioma, focusing on its impact on RNA splicing regulation." (PMID 40365337, 2025). "Disruption of these pathways following LSM2 knockdown likely impairs glioma cell proliferation and makes the tumour cells more vulnerable to environmental stress." (PMID 40365337, 2025). "Future studies should focus on further exploring the precise mechanisms by which LSM2 influences tumour behaviour and immune responses, with the ultimate goal of developing effective therapies for glioma patients." (PMID 40365337, 2025). "Our results corroborate these findings, demonstrating that LSM2 expression is significantly upregulated in gliomas, especially in GBM, and correlates with poor prognosis." (PMID 40365337, 2025). "LSM2’s role in regulating these pathways highlights its potential as both a prognostic biomarker and a therapeutic target for gliomas." (PMID 40365337, 2025). "Knockdown of LSM2 significantly impacted glioma cell behaviour, with alterations observed in critical pathways that regulate tumour proliferation, survival, and invasiveness." (PMID 40365337, 2025). "Given the importance of splicing in tumour progression, these findings emphasise LSM2’s pivotal role in driving glioma progression through splicing regulation." (PMID 40365337, 2025).
glioma (continued). "The significant role of LSM2 in glioma progression presents several promising therapeutic opportunities." (PMID 40365337, 2025). "Our study highlights LSM2 as a critical player in glioma progression, particularly through its regulation of RNA splicing and its impact on key pathways involved in tumour biology, such as cell adhesion, DNA repair, and immune modulation." (PMID 40365337, 2025). "These hub genes —key regulators of cytoskeletal dynamics and cell migration—implies that LSM2 may promote glioma progression by dysregulating these effector molecules, potentially via aberrant splicing of their pre-mRNAs." (PMID 40365337, 2025). "Our investigation revealed elevated LSM2 expression in gliomas through exploration of the TCGA database, LSM2 expression is significantly higher in GBM compared to lower-grade gliomas (LGG), and its expression correlates with the presence of IDH1 mutations and the 1p/19q non-deletion status." (PMID 40365337, 2025). "This study aims to investigate the expression of LSM2 in glioma, its prognostic significance, and the molecular mechanisms through which it influences glioma biology, focusing particularly on its role in alternative splicing and its potential as a therapeutic target." (PMID 40365337, 2025). "Understanding how LSM2 interacts with immune cells and modulates their activity could open new avenues for glioma treatment, particularly in combination with immunotherapy." (PMID 40365337, 2025). "Given the central role of LSM2 in RNA processing and the critical nature of RNA splicing in tumourigenesis, we hypothesise that LSM2 plays a crucial role in glioma progression by modulating RNA splicing events, thereby contributing to tumour aggressiveness and poor patient prognosis." (PMID 40365337, 2025). "However, there are still few studies on the role of LSM2 in gliomas." (PMID 40365337, 2025). "Subgroup analysis by glioma histological type demonstrated higher LSM2 expression in GBM compared to astrocytomas, oligodendrogliomas, and mixed gliomas." (PMID 40365337, 2025). "In contrast, in lower-grade gliomas (LGG), LSM2 expression showed a positive correlation with tumour purity and CD4+ T cell infiltration, but a negative correlation with CD8+ T cell infiltration." (PMID 40365337, 2025). "A pan-cancer analysis of LSM2 expression using the GEPIA database revealed significantly higher expression of LSM2 in tumour samples compared to normal samples across various cancer types, including glioblastoma (GBM) and lower-grade glioma (LGG) (p < 0.05)." (PMID 40365337, 2025). "Upon isolating cells based on risk score gene expression levels, we found that cells with higher LSM2 expression had lower immune scores, while those with elevated OSMR expression had higher immune scores, reinforcing the roles of LSM2 and OSMR in glioma immunity." (PMID 41498024, 2025). "LSM2 expression was significantly elevated in gliomas, particularly in GBM and in tumours with 1p/19q non-deletion or IDH1 mutation (p < 0.001)." (PMID 40365337, 2025). "Specifically, LSM2 depletion resulted in the upregulation of extracellular matrix (ECM) genes like FN1 and COL1A1, which could disrupt tumour cell-ECM interactions and potentially diminish the invasive phenotypes of glioma cells." (PMID 40365337, 2025). "Furthermore, LSM2 expression was significantly higher in gliomas with 1p/19q non-deletion (494 cases) than in those with 1p/19q co-deletion (169 cases) (p < 0.001), as well as in IDH1-mutant gliomas (429 cases) compared to IDH1 wild-type cases (233 cases) (p < 0.001)." (PMID 40365337, 2025).
glioblastoma multiforme (3 papers, 2022 to 2025). "We also explore the functional consequences of LSM2 knockdown in glioblastoma cells, aiming to uncover key genes and pathways regulated by LSM2." (PMID 40365337, 2025). "RNA sequencing was performed on LSM2 knockdown in T98G glioblastoma cells to identify differentially expressed genes (DEGs) and alternative splicing events (ASEs)." (PMID 40365337, 2025).
hepatocellular carcinoma (3 papers, 2023 to 2025). A malignant tumor that arises from hepatocytes. "Consistent with previous findings in GBM, hepatocellular carcinoma, and melanoma, our study confirms that elevated LSM2 expression signifies a poor prognosis and it may act as a common oncogenic factor across different cancer types." (PMID 41498024, 2025).
melanoma (3 papers, 2022 to 2025). A malignant, usually aggressive tumor composed of atypical, neoplastic melanocytes. "Upregulated LSM2 was positively correlated with melanoma ulcers, advanced TNM stage, high Clark level, and deep Breslow depth." (PMID 37312186, 2023). "We evaluated the gene effect scores of LSM2 in melanoma cell lines using “Data Explore” module in DepMap." (PMID 37312186, 2023). "In the univariate analysis, age, race, melanoma ulceration, TNM stage, pathologic stage, and LSM2 expression were significantly related to the prognosis of SKCM in the TCGA database." (PMID 36371223, 2022).
Cirrhosis (2 papers, 2020 to 2021). A chronic disorder of the liver in which liver tissue becomes scarred and is partially replaced by regenerative nodules and fibrotic tissue resulting in loss of liver function. "We observed decreased values of the LSM2/LSM1 ratio and the rate of cirrhosis progression in rs1801133 T allele carriers." (PMID 33304912, 2020). "The presence of the rs1801133 C allele showed an inverse association with the LSM2/LSM1 ratio (adjusted AMR = 0.90; 95%CI = 0.83–0.98; p = 0.020) and the cirrhosis progression (adjusted OR = 0.43; 95%CI = 0.19–0.95; p = 0.038)." (PMID 33304912, 2020). "Besides, rs1801133 CT/CC genotype had an inverse association with the LSM2/LSM1 ratio (adjusted AMR = 0.80; 95%CI = 0.68–0.95; p = 0.009) and the cirrhosis progression (adjusted OR = 0.21; 95%CI = 0.06–0.74; p = 0.015)." (PMID 33304912, 2020). "Moreover, rs886277 CC genotype was also related to higher values of LSM2/LSM1 ratio (adjusted arithmetic mean ratio a(AMR) = 1.31; p = 0.001) and cirrhosis progression (aOR = 4.33; p = 0.027)." (PMID 33525598, 2021).
acute myeloid leukemia (1 paper, 2022). Acute myeloid leukemia (AML) is a group of neoplasms arising from precursor cells committed to the myeloid cell-line differentiation. "Meanwhile, LSM2 expression was decreased in kidney chromophobe (KICH) and acute myeloid leukemia (LAML)." (PMID 36371223, 2022).
autoimmune disease (1 paper, 2024). A disorder resulting from loss of function or tissue destruction of an organ or multiple organs, arising from humoral or cellular immune responses of the individual to their own tissue constituents. "Six genes in the MHC Class III region, DDX39B, DXO, LSM2, NELFE, PRRC2A, and SKIV2L, encode RBPs and have a well-defined role in post-transcriptional gene regulation and RNA monitoring, and these genes may have important functions in immunity and be associated with autoimmune diseases." (PMID 38770048, 2024).
breast tumors (1 paper, 2021). "Methylation levels of LSM2, LSM4, and LSM10 were upregulated in primary breast tumors, while LSM6 methylation levels were downregulated." (PMID 34638387, 2021). "Of interest, our findings through DNA methylation level analysis by using UALCAN database also support the consistent trend, which show LSM2, LSM4, LSM10 were upregulated in primary breast tumors, while LSM6 methylation levels were downregulated." (PMID 34638387, 2021).
Fanconi anaemia (1 paper, 2025). "Downregulated DEGs were enriched in homologous recombination (15 genes, p < 0.05) and the Fanconi anaemia pathway (17 genes, p < 0.05), indicating that LSM2 knockdown may affect DNA repair and genome stability." (PMID 40365337, 2025).
nasopharyngeal carcinoma (1 paper, 2023). A carcinoma arising from the nasopharyngeal epithelium. "Another study verified the overexpression of LSM2 in nasopharyngeal carcinoma (NPC) tissues using IHC." (PMID 37312186, 2023).
cancer (9 papers, 2014 to 2025). A tumor composed of atypical neoplastic, often pleomorphic cells that invade other tissues. "We investigated mutations of LSM genes in BRCA patients from TCGA Pan-Cancer Atlas (n = 1082 patients) in the cBioPortal platform, and found surprisingly high rates of alterations in LSM1 (25%), LSM2 (11%) LSM4 (8%), and LSM14B (23%)." (PMID 34638387, 2021). "In addition, we analyzed the associations between LSMs (LSM2 and LSM4) and the expression of immunoinhibitors, immunostimulators, and MHC molecules in various types of human cancers." (PMID 36371223, 2022). "Pan-cancer analysis indicated the aberrant expression of LSM2 in human cancers." (PMID 36371223, 2022).